MTF1 (metal regulatory transcription factor 1)
Description:
Zinc-dependent transcriptional regulator of cellular adaption to conditions of exposure to heavy metals. Binds to metal responsive elements (MRE) in promoters and activates the transcription of metallothionein genes like metallothionein-2/MT2A. Also regulates the expression of metalloproteases in response to intracellular zinc and functions as a catabolic regulator of cartilages (By similarity).
Synonyms: MTF-1; ZRF
Tractability: PROTAC: ubiquitination databases record sites on it.
Gene: Protein-coding gene on chromosome 1 (37,809,574 to 37,859,614, reverse strand). Ensembl gene ENSG00000188786.
Subcellular location: Nucleus; Cytoplasm
Subcellular location (Human Protein Atlas): Nucleoplasm
Pathways (Reactome):
Metabolism: Activation of gene expression by SREBF (SREBP); PPARA activates gene expression
Cellular responses to stimuli: MTF1 activates gene expression
Gene Ontology:
Molecular function: cis-regulatory region sequence-specific DNA binding; DNA-binding transcription activator activity, RNA polymerase II-specific; protein binding; RNA polymerase II cis-regulatory region sequence-specific DNA binding; sequence-specific double-stranded DNA binding; DNA binding; DNA-binding transcription factor activity; histone acetyltransferase binding
Biological process: positive regulation of transcription by RNA polymerase II; central nervous system development; regulation of transcription by RNA polymerase II; response to metal ion; cellular response to zinc ion; DNA-templated transcription
Cellular component: nucleoplasm; nucleus; cytoplasm
Genetic constraint (gnomAD): Loss-of-function variants: 17 observed, 61.2 expected, observed/expected ratio (o/e) 0.28, 90% interval 0.19 to 0.42. The upper end of that interval is the gene's LOEUF score, 0.42, which puts it in group 1 of 6, group 1 being the genes least tolerant of losing a copy. Missense variants: 619 observed, 905.37 expected, observed/expected ratio (o/e) 0.68, 90% interval 0.64 to 0.73. Synonymous variants: 312 observed, 351.02 expected, observed/expected ratio (o/e) 0.89, 90% interval 0.81 to 0.98.
Homologues: Orthologues: chimpanzee MTF1 (99% identical), macaque MTF1 (99% identical), dog MTF1 (94% identical), pig MTF1 (91% identical), rabbit MTF1 (91% identical), rat Mtf1 (83% identical), mouse Mtf1 (83% identical), guinea pig MTF1 (82% identical), tropical clawed frog mtf1 (57% identical), zebrafish mtf1 (54% identical), Drosophila melanogaster MTF-1 (30% identical). Paralogues in human: ZNF281 (16% identical), ZNF76 (16% identical), ZNF143 (15% identical), ZNF148 (14% identical), PRDM10 (13% identical), PATZ1 (12% identical), VEZF1 (12% identical), ZNF384 (12% identical), PRDM1 (11% identical), ZNF451 (11% identical), ZNF410 (11% identical), ZNF362 (10% identical), and 24 more.
Diseases named in the same sentence as MTF1 in open-access papers:
MTF1 is named in the same sentence as 112 diseases in open-access papers, as found by Europe PMC text mining. Sharing a sentence is not in itself a finding about the gene and the disease. The quoted sentences say what the papers report.
ovarian carcinoma (16 papers, 2020 to 2025). A malignant neoplasm originating from the surface ovarian epithelium. "A study found that MTF1 was upregulated in ovarian cancer, and its high expression was associated with poor patient survival and disease relapse." (PMID 36247012, 2022). "Furthermore, lower expression levels of ACO1, HFE, IREB2, and MTF1 in iron regulation were associated with an advanced stage of ovarian cancer." (PMID 38186569, 2023). "Previously, MTF1 knockout reduced the proliferation, migration, and invasion of two types of ovarian cancer cells." (PMID 38943058, 2024). "The expression of MTF1 and BMP6 involved in iron regulation was associated with improved OS in ovarian cancer, whereas the expression of IREB2, GPI, and HMOX1 in this process was associated with poor OS in ovarian cancer." (PMID 38186569, 2023). "High expression of MTF1 also showed good OS for the ovarian cancer patients treated with multiple chemotherapy agents, including gemcitabine, paclitaxel, platin and topotecan." (PMID 37380924, 2023). "The Kaplan–Meier plotter portrayed that high MTF1 expression was linked with good OS, FP and PPS in lung cancer, good OS, PPS and PFS in ovarian cancer and good OS, PPS, RFS and DMFS in breast cancer." (PMID 37380924, 2023). "The expression of HFE, MTF1, and BMP6 involved in iron regulation was associated with improved PFS in ovarian cancer, whereas the expression of HIF1A, GPI, and HAMP involved in this process was associated with poor PFS in ovarian cancer." (PMID 38186569, 2023). "Another study has evaluated the expression levels of MTF1 in ovarian cancer samples and found the upregulated expression of MTF1 in ovarian cancer." (PMID 37380924, 2023). "MTF1 is an important component of the metal regulatory system in mammalian cells, and the knockdown of MTF1 inhibits the epithelial-to-mesenchymal transition in ovarian cancer cells." (PMID 36211401, 2022). "According to a previous study, knockout of MTF1 inhibits ovarian cancer cell proliferation, migration, and invasion by suppressing epithelial-to-mesenchymal transition." (PMID 36386799, 2022). "Also, high expression level of MTF1 was associated with good prognosis of kidney renal clear cell carcinoma (KIRC), lung cancer, ovarian cancer and breast cancer." (PMID 37380924, 2023). "Knockdown of MTF1 by lentiviral CRISPR/Cas9 could obviously suppress the metastasis of ovarian cancer cells." (PMID 37380924, 2023). "In ovarian cancer, the knockdown of MTF1 expression suppressed EMT in ovarian cancer cells." (PMID 36117848, 2022). "MTF1 plays an oncogenic role and leads to ovarian cancer metastasis by inducing EMT pathways." (PMID 36581992, 2022). "Also, the ovarian cancer patients with higher MTF1 expression displayed good OS, PPS and PFS." (PMID 37380924, 2023). "Therefore, knockout of MTF1 inhibited EMT in ovarian cancer cells." (PMID 36703728, 2022). "In ovarian cancer, MTF1 might be a new biomarker for prompt diagnosis and aid in targeted therapy." (PMID 36312586, 2022). "High expression of MTF-1 was proven to increase zinc-induced activation of ERK1/2 and AKT, thereby inducing the progression of ovarian cancer." (PMID 39308676, 2024). "Similar findings were observed in the ovarian cancer cell line HEY, where reconstitution with MTF1 S152A mutant, but not the S152D mutant, significantly rescued MTF1 KO HEY cell viability and xenograft tumor growth under cisplatin treatment." (PMID 39920630, 2025).
glioma (13 papers, 2020 to 2025). A benign or malignant brain and spinal cord tumor that arises from glial cells (astrocytes, oligodendrocytes, ependymal cells). "Our results in the heatmap indicated that MTF1 had strong correlations with 14 tumors' functional status in many kinds of cancers, among which high-grade glioma (HGG), retinoblastoma (Rb), and UVM were the most significant." (PMID 39308676, 2024). "Taken together, the TAF15/LINC00665/MTF1(YY2)/GTSE1 axis has been acknowledged as an important axis in the modulation of the malignant features of glioma cells." (PMID 36429005, 2022). "LINC00665 promoted MTF1 degradation, and MTF1 bound to the promoter region of GTSE1 and transcription promoted GTSE1 expression, which proved that LINC00665/MTF1/GTSE1 axis played an important role in regulating the biological behavior of glioma cells." (PMID 36110851, 2022). "The PABPC1-BDNF-AS-RAX2-DLG5 axis was shown to play the same role as the TAF15/LINC00665/MTF1(YY2)/GTSE1 axis in regulating the biological behavior of gliomas." (PMID 34178684, 2021). "Furthermore, MTF1 has been reported to have biological significance in several cancer subtypes and has been proposed as a novel prognostic biomarker in low-grade glioma." (PMID 41389090, 2025). "However, another research has also found that MTF1 shows high expression levels in glioma cells, and its knockout inhibits malignant progression." (PMID 37152283, 2023). "Moreover, we identified the up-regulated MTF1 expression in liver cancer and glioma." (PMID 37380924, 2023). "Finally, MTF1 or YY2 silencing has reduced expression of GTSE1 oncogene in glioma." (PMID 36429005, 2022). "A recent study on glioma cell lines (U251 and U87) further demonstrated that STAU1 blocks cell migration and invasion by degrading metal regulatory transcription factor 1 (MTF1) and YY2 transcription factor (YY2) through SMD." (PMID 34633481, 2021). "For example, LINC00665 is downregulated in glioma and mediates STAU1-mediated MTF1 and YY2 stability, affecting malignant biological behavior of glioma." (PMID 32851059, 2020). "Additionally, overexpression of TAF15 stabilizes LINC00665, leading to reduced STAU1-mediated mRNA degradation of both MTF1 and YY2, thereby restricting GTSE1 transcription and ultimately disrupting glioma’s malignant progression." (PMID 37403043, 2023). "Moreover, MTF1 and YY2 transcription factor have been shown to be over-expressed in glioma cells, and their silencing has suppressed malignant behaviors of these cells." (PMID 36429005, 2022). "However, another view is that LINC00665 can act as a protective factor for glioma, inhibiting the malignant development of the tumor through the TAF15|LINC00665/MTF1|YY2/GTSE1 axis." (PMID 35563845, 2022). "In glioma, the TAF15|LINC00665/MTF1|YY2/GTSE1 axis inhibits malignant tumor progression.TATA-box-binding protein-associated factor 15 (TAF15) is a member of the FET family and plays an important role in regulating mRNA transcription, RNA splicing, and trafficking." (PMID 35563845, 2022). "For OS outcomes of glioma patients, a 9-gene signature was selected to construct the prognostic score using their regression coefficients: Riskscore = (0.8949)*FDX1 + (0.4902)*DLD + (0.0778)*DLAT + (-0.9324)*LIAS + (0.1132)*GLS + (0.903)*LIPT1 + (-0.1847)*MTF1 + (-0.2352)*PDHA1 + (-0.2045)*PDHB." (PMID 36915038, 2023). "In addition to the levels of GLS, MTF1, and PDHB, those of the other seven CRGs significantly affected the OS, DSS, and PFI of glioma patients; cuproptosis may play a major role in disease progression." (PMID 36579333, 2022). "Additionally, the TAF15/LINC00665/MTF1(YY2)/GTSE1 axis is crucial for regulating the malignant biological behaviors of glioma cells, which might help in the development of a novel therapeutic strategy for human glioma." (PMID 34178684, 2021).
breast carcinoma (11 papers, 2019 to 2024). "Mutation analysis showed that 32% of breast cancer samples had MTF1 genetic mutations." (PMID 36312586, 2022). "Future research should focus on validating the cuproptosis-related gene signature in diverse cohorts and exploring the functional roles of the lncRNA XIST/miR-92b-3p/MTF1 axis in breast cancer progression." (PMID 39867656, 2024). "The breast cancer patients with high expression levels of MTF1 displayed good OS, PPS, relapse-free survival (RFS) and distant metastasis free survival (DMFS)." (PMID 37380924, 2023). "In prognosis analysis of GSE20865 cohort, the data affirmed a better OS and RFS rate in breast cancer patients with elevated MTF1 expression levels (p < 0.05)." (PMID 36312586, 2022). "Our study also ascertained the lncRNA XIST/miR-92b-3p/MTF1 regulatory axis for the progression of breast cancer." (PMID 36312586, 2022). "Consistent with the previous data, immunohistochemistry revealed that MTF1 was medium staining in normal tissue while it was low staining in breast cancer tissue." (PMID 36312586, 2022). "Univariate as well as multivariate analyses indicated that MTF1 expression, age, and pTNM stage were independent factors influencing the breast cancer patient's prognoses." (PMID 36312586, 2022). "Among these miRNAs, only miR-92b-3p was differentially expressed in breast cancer, so we selected miR-92b-3p as a miRNA target of MTF1." (PMID 36312586, 2022). "Moreover, high MTF1 expression of breast cancer patients treated with chemotherapy or endocrine therapy displayed good OS." (PMID 37380924, 2023). "We afterward validated the prognostic value of MTF1 in breast cancer." (PMID 36312586, 2022). "Finally, we conducted an lncRNA-miRNA-mRNA regulatory axis analysis to elucidate the role of MTF1 in breast cancer." (PMID 36312586, 2022). "The lncRNA XIST/miR-92b-3p/MTF1 regulatory axis may be important in breast cancer progression." (PMID 36312586, 2022). "Moreover, we identified the lncRNA XIST/miR-92b-3p/MTF1 regulatory axis for breast cancer." (PMID 36312586, 2022). "Prognosis analysis revealed poor OS and RFS rates in breast cancer patients with elevated levels of CDKN2A and PDHA1 and low levels of MTF1, DLD, LIPT1, and FDX1." (PMID 36312586, 2022). "Multiomics approaches were used to create a cuproptosis-related signature with six genes (DKN2A, MTF1, PDHA1, DLD, LIPT1, and FDX1) for breast cancer." (PMID 36312586, 2022). "In conclusion, multiomics approaches were conducted to develop a cuproptosis-related signature with six genes (DKN2A, MTF1, PDHA1, DLD, LIPT1, and FDX1) for breast cancer." (PMID 36312586, 2022). "The results revealed that the expression of MTF1 (p = 0.037) and LIPT1 (p = 0.021) decreased as the pTNM stage increased in breast cancer." (PMID 36312586, 2022). "We then constructed a cuproptosis-related signature with six genes (DKN2A, MTF1, PDHA1, DLD, LIPT1, and FDX1) for breast cancer, which predicted the OS rate with an accuracy that ranged from medium to high." (PMID 36312586, 2022). "FDX1 (P < 1E‐12), LIAS (P = 2.22E‐16), LIPT1 (P < 1E‐12), DLD (P < 5.46E‐09), DLAT (P = 3.14E‐02), PDHA1 (P = 1.15E‐07), MTF1 (P = 1.07E‐09), and GLS (P = 2.48E‐05) were downregulated in breast cancer, while PDHB (P = 5.04E‐07) and CDKN2A (P = 1.62E‐12) were upregulated." (PMID 39432636, 2024). "We discovered the lncRNA XIST/miR-92b-3p/MTF1 regulatory axis for breast cancer, which has not yet been investigated previously." (PMID 36312586, 2022). "We identified the lncRNA XIST/miR-92b-3p/MTF1 regulatory axis for breast cancer, which has not been studied before." (PMID 36312586, 2022).
breast carcinoma (continued). "Another vital discovery of our research was that we developed a cuproptosis-related prognostic signature containing six genes (CDKN2A, MTF1, PDHA1, DLD, LIPT1, and FDX1) for breast cancer, which predicted the OS rate with an accuracy that ranged from medium to high." (PMID 36312586, 2022). "Our study determined the lncRNA XIST/miR-92b-3p/MTF1 regulatory axis for breast cancer, which has not been studied before." (PMID 36312586, 2022). "We analyzed the expression pattern of CRGs in breast cancer tissues and non-tumor tissues based on TCGA and GTEx dataset, illustrating that CDKN2A, DLD, DLAT, MTF1 and PDHB expression were significantly elevated in breast cancer compared with their normal tissues." (PMID 36518756, 2022).
lung adenocarcinoma (6 papers, 2022 to 2025). A carcinoma that arises from the lung and is characterized by the presence of malignant glandular epithelial cells. "A study has studied the crucial role of cuproptosis-related genes (CRGs) in lung adenocarcinoma and found that MTF1, SLC31A1, FDX1 and DLD were associated with the tumor microenvironment and immune responses in lung adenocarcinoma." (PMID 37380924, 2023). "Clinically, lung adenocarcinoma (LUAD) patients with high MTF1 activity exhibit poor overall survival rates, and Hippo pathway inactivation is positively correlated with elevated MTF1 transcriptional activity in platinum-treated LUAD patients." (PMID 39920630, 2025). "MTF1 is down-regulated in most cancers, including lung adenocarcinoma and lung squamous cell carcinoma, and higher expression of MTF1 may predict a better prognosis for LC patients." (PMID 38943058, 2024). "To determine the clinical relevance of the Hippo-MTF1 pathway, we analyzed data from The Cancer Genome Atlas (TCGA) regarding the expression of MTF1 and its downstream genes MT1A and MT2A in lung adenocarcinoma (LUAD) cancer patients." (PMID 39920630, 2025). "By systematically analyzing the genetic alterations of 10 cuproptosis-related genes in lung adenocarcinoma, we found that CDKN2A, DLAT, LIAS, PDHA1, FDX1, GLS, and MTF1 were differentially expressed between lung cancer tissues and adjacent tissues." (PMID 36712848, 2022). "It is reported that lung adenocarcinoma cells lacking MTF1 will be more sensitive to oxidative stress." (PMID 36902801, 2023). "Lung adenocarcinoma cells lacking MTF1 are more sensitive to oxidative stress." (PMID 38943058, 2024). "In this research, samples of lung adenocarcinoma were interrogated with cuproptosis-related genes, among which high expression of DLD, DLAT, PHDA1, PHDB, and CDKN2A were correlated with poor OS, while high expression of MTF1 was correlated with longer OS compared with the MTF1 low expression." (PMID 36003780, 2022).
ovarian tumor (6 papers, 2020 to 2024). "Another study revealed that zinc contributes to ovarian tumor metastasis by promoting epithelial to mesenchymal (EMT) transition through a MTF1 dependent pathway." (PMID 36703728, 2022). "MTF1 has cancer-causing actions and encourages EMT, which aids in the spread of ovarian tumors." (PMID 36891324, 2023). "Similarly, zinc is a contributor to ovarian tumor metastasis by promoting EMT through a MTF1 (Metal Response Transcriptional Factor-1) mediated pathway that involves ERK1/2 and AKT." (PMID 34988012, 2021). "Liang and his colleagues demonstrated that over-expressed MTF1 can promote epithelial-mesenchymal transition (EMT) and ovarian tumor metastasis, making it a potential new biomarker for early diagnosis of ovarian cancer." (PMID 38388534, 2024). "We have identified the selective signal in metal responsive transcription factor 1 (MTF1, LRT p value = 9.85 × 10−5), which is upregulated in malignant ovarian cancer and might contribute to ovarian tumor metastasis." (PMID 37395176, 2023).